SOX10 (SRY-box transcription factor 10)
Diseases named in the same sentence as SOX10 in open-access papers (continued):
Sharing a sentence is not in itself a finding about the gene and the disease.
melanoma (continued). "Then, the miRNAs between TCGA and TargetScan were generated by using Venn diagram, which showed that 2 miRNAs, miRNA-222-3p and miRNA-221-3p, were negatively and directly correlated with SOX10 in melanoma patients." (PMID 35585935, 2022). "Tissue microarray analysis indicates that DEPDC1B expression is positively correlated with SOX10 in the different stages of melanoma." (PMID 35088579, 2022). "Curcumin enhances the miR-222-3p level to reduce SOX10 expression and ultimately inactivates the Notch pathway in melanoma." (PMID 35585935, 2022). "Primary tumors developed from the MITF-methylated SOX10+ and SOX10– melanoma cells were molecularly different and had different preferential metastatic spread." (PMID 36040798, 2022). "It has been indicated that SOX10 impedes the immunogenicity of melanoma cells through the IRF4-IRF1 axis." (PMID 35585935, 2022). "Treatment of SOX10 KD cells with DEPDC1B OE resulted in the partial rescue of melanoma cell proliferation, colony formation, invasion, lung metastasis, and CD31+ microvessel formation in lung nodules compared with SOX10 KD alone." (PMID 35088579, 2022). "We next counted the SOX10+ melanoma cells that paired with CD8+ T cells and normalized the pairs to the total CD8+ T-cell number since CD8+ T-cell number was not altered due to therapy." (PMID 35058553, 2022). "In melanoma, FTO promoted cell proliferation and overall tumorigenicity by demethylating m6A on melanoma-promoting genes Pdcd1, Cxcr4, and Sox10." (PMID 35350378, 2022). "Together, we performed integrated approaches to identify SMARCA4 as a promising prognostic marker for melanoma, which was transcriptionally regulated by SOX10 and promoted melanoma cell proliferation by ameliorating DNA replication stress." (PMID 36317703, 2022). "An automated, IHC-supervised annotation technique with high precision was developed for melanoma and subcutaneous metastases by means of digital H&E/SOX10 dual stains with a red chromogen." (PMID 36361209, 2022). "Upstream of MITF, reduced SOX10 expression has been reported throughout melanoma development, from early to metastatic stages." (PMID 36040798, 2022). "The MITF and SOX10 transcription factors act as important regulators of melanoma phenotypic-state transition and control invasive and metastatic features of melanoma." (PMID 35159386, 2022). "Studies have found a reactivation of an NC program in melanoma, and indeed we observed upregulation of NC genes such as crestin, sox10, tfap2a, dlx2a, among others." (PMID 34791221, 2022). "Our analyses of dedifferentiated melanomas support 2 distinct phenotypes with similarities in MITF promoter methylation but differences in SOX10 mRNA levels and DNA methylation status." (PMID 36040798, 2022). "Similar studies have shed light on the epigenetic regulation of dysregulated genes that promote melanoma, such as sox10, or have been used to delineate developmental programs underlying erythroid differentiation." (PMID 34791221, 2022). "Sex-determining region Y (SRY)-related HMG box-containing factor 10 (SOX10) participates in melanoma genesis." (PMID 36078157, 2022). "It has been evidenced that SOX10 negatively regulates LACTB’s transcription in melanoma cells by binding to its promoter." (PMID 36078157, 2022). "Consistently, DEPDC1B is both required and sufficient for melanoma growth, metastasis, angiogenesis, and functions as a direct downstream target of SOX10 to partly mediate its oncogenic activity." (PMID 35088579, 2022). "One of the most evident up-regulated melanoma specific transcription factors expressed in all melanoma cell lines was SOX10, while several proteins related to melanogenesis were increased only in MITF positive cell lines." (PMID 36776379, 2022). "Here, we demonstrated that SOX10 regulates expression of DEPDC1B which sequesters ubiquitin ligase CDC16 to stabilize the secreted SCUBE3 protein for promoting melanoma growth, angiogenesis, and metastasis." (PMID 35088579, 2022).
melanoma (continued). "Previous studies have shown that melanoma reactivates aspects of an embryonic NC program, with prominent NC genes such as sox10 the subject of much interest." (PMID 34791221, 2022). "SOX10 expression was localised to the nucleus of melanoma cells with minimal branches into the cytoplasm of cells." (PMID 35664673, 2022). "This staining pattern is different from melanoma, which is normally diffusely positive for SOX10 and S100, along with more specific melanoma markers, including Melan-A and HMB45." (PMID 36135073, 2022). "In our previous study, we found that sex-determining region Y-related high mobility group-box 10 (SOX10) was an oncogenetic role in melanoma progression, especially in proliferation." (PMID 35585935, 2022). "The panel included the immune cell markers CD8, CD68, CD16, the immune checkpoint PD-L1, and melanoma tumour marker SOX10." (PMID 35664673, 2022). "Consecutive sections of the MRD site were stained with mCherry and Sox10 antibodies and confirmed that the mCherry+ cells were Sox10+ persister melanoma cells." (PMID 35929478, 2022). "Because metastases, in general, display a higher proliferative potential than primary melanomas, a low SOX10 expression of metastases seems justified." (PMID 36361209, 2022). "This type of tumor regularly expresses melanocytic markers such as HMB45 and Melan A, but much less rarely expresses S100 or SOX10, which are always positive in melanomas with an epithelioid or spindle-shaped morphology." (PMID 36564790, 2022). "Immunostaining confirmed the expression of Melan-A, SRY-box transcription factor 10 (Sox10), human melanoma black-45 (HMB-45), and tyrosinase-related protein 1 (TRP1) (green) in all cultured CD90−CD117+ cells." (PMID 35269891, 2022). "The 3 different SOX10– melanoma cell lines also displayed increased colony formation capacity in a 2-week assay, and colonies appeared structurally and morphologically different at the microscopic level (P = 0.0001)." (PMID 36040798, 2022). "SOX10 has been identified as a driver of melanoma progression, a cancer that develops from melanocytes which are neural crest derivatives." (PMID 36496864, 2022). "Though more of their SOX10-positive metastases were weakly stained (10 of 10; 100%) compared with primary melanomas (15 of 21; 71%), approximately half of both lesion types were SOX10-negative." (PMID 36361209, 2022). "It is known that depletion of SOX10 reduces cell proliferation and induces senescence, and that Sox10 over-expression in zebrafish promotes melanoma formation." (PMID 35296667, 2022). "Our study indicated that curcumin serves a key role in the suppression of melanoma cell proliferation, migration, and invasion via enhancing miR-222-3p which targeted to SOX10." (PMID 35585935, 2022). "Taken together, the curcumin enhances the miR-222-3p level to inhibit SOX10 expression, which inactivates the Notch pathway to impede the melanoma cell proliferation, migration, and invasion." (PMID 35585935, 2022). "The most important tool in confirming the melanoma diagnosis was IHC with melanoma markers SOX10, S100, HMB45, and Melan-A." (PMID 36289768, 2022). "By means of digital H&E/SOX10 dual stains with a red chromogen, a large annotated H&E training set with high quality was created within a reasonable timeframe for primary melanomas and metastases of the skin." (PMID 36361209, 2022). "Meanwhile, SMARCA4 was reported to regulate SOX10 expression or function as a co‐activator of SOX10 in melanoma." (PMID 36317703, 2022). "In order to further explore the molecular mechanism of curcumin regulating SOX10, we made a correlation analysis among SOX10 and miRNAs based on TCGA database Melanoma datasets." (PMID 35585935, 2022). "Another set of data suggests that melanoma formation in vitro and in vivo is counteracted by the inactivation of neural crest stem cell factor SOX10." (PMID 35719931, 2022).
melanoma (continued). "At experimental termination, in NSG mice transplanted with the SOX10– IGR-39 melanoma cell line, only 8 out of the 10 mice developed tumors." (PMID 36040798, 2022). "We further observed that the primary tumors from SOX10– IGR-39 engrafted NSG mice remained negative for MITF and SOX10 protein expression, while we found scattered MITF+ melanoma cells in the primary tumors derived from SOX10+ MM383 engrafted NSG mice." (PMID 36040798, 2022). "As the expression of SOX10 is known in melanoma and other tumors of other neural lineages, its expression in breast carcinoma is not explained in the literature and can be a pitfall for pathologists." (PMID 36120242, 2022). "Frequencies of SOX10+ TNFR2+ melanoma were elevated in all three patients by week 3, prior to the administration of IFN-α2b therapy." (PMID 35879777, 2022). "In this study, we have explored how the melanocyte differentiation–specific transcription factors, MITF and SOX10, are epigenetically regulated and determine melanoma aggressiveness, cell phenotype, and therapy response." (PMID 36040798, 2022). "Immunofluorescence analysis of a tissue microarray showed extensive overlap in the expression of SOX10, which is as key driver of melanoma initiation and progression, and the expression of DEPDC1B in the different stages of melanoma." (PMID 35088579, 2022). "The NCSC-like melanoma cells express the transcription factor SOX10, while the undifferentiated melanoma cells have concomitant loss of MITF and SOX10." (PMID 36040798, 2022). "Our findings demonstrate that SOX10 is heterogeneously expressed in treatment-naïve melanoma samples." (PMID 35296667, 2022). "Curcumin enhances the miR-222-3p level to reduce SOX10 expression, and ultimately inactivates the Notch pathway in repressing melanoma proliferation, migration, and invasion." (PMID 35585935, 2022). "Pearson regression results from 4 different melanoma databases showed that SOX10 and USF2 were positively correlated with the expression of SMARCA4, yet TBX15 and ETS2 were negatively correlated with the expression of SMARCA4." (PMID 36317703, 2022). "The present study found curcumin inactivates Notch signaling pathway by regulating miR-222-3p/SOX10 axis in melanoma cell." (PMID 35585935, 2022). "An oncogenic mechanism is unraveled by which DEPDC1B functions downstream of SOX10 to promote melanoma angiogenesis and metastasis." (PMID 35088579, 2022). "This is one of the first studies to compare the intensity level of SOX10-positive cells in primary melanomas and various types of metastatic melanoma by image analysis (chromaticity red)." (PMID 36361209, 2022). "Due to low or missing tumor-cell SOX10 positivity, precision for normal cells was markedly reduced in lymph-node and organ metastases compared with primary melanomas (p < 0.001)." (PMID 36361209, 2022). "In conclusion, it is revealed that a SOX10‐DEPDC1B‐SCUBE3 regulatory axis promotes melanoma angiogenesis and metastasis, which suggests that targeting secreted SCUBE3 can be a therapeutic strategy against metastatic melanoma." (PMID 35088579, 2022). "The data show that those patients with a high number of SOX10+ melanoma cells at progression and a higher number of SOX10 & CD8+T-cell pairs had a significantly shorter PFS (Spearman r = −0.75, p = 0.025)." (PMID 35058553, 2022). "We observed a significant increase in SOX10+ melanoma cells in the progressed tumors compared to the tumors prior to BRAF/MEK-inhibition from the same patient." (PMID 35058553, 2022). "We used an antibody against the mCherry protein to label the ‘switched’ cells in tamoxifen-treated fish compared to DMSO control, together with antibodies against the melanoma markers Sox10 and Mitfa." (PMID 35929478, 2022). "To pursue the observation of preferential brain metastasis in SOX10– melanoma, we performed a melanoma cell migration experiment based on organotypic brain slice cultures." (PMID 36040798, 2022).
melanoma (continued). "A SOX10-deficient, slow-cycling state has been implicated in acquired resistance of BRAF-mutant melanoma to BRAFi through upregulation of TGFβ1-EGFR signaling." (PMID 35296667, 2022). "In comparison, the SOX10+MITF– NCSC-like melanoma cell lines had acquired expression of other NC-derived lineage markers such as SOX2 (expressed in glial lineages), SOX5, and SOX8 (expressed in neural progenitors)." (PMID 36040798, 2022). "Melanoma cell hTERT expression was determined by co-staining for Sox10/S100 and hTERT and was confirmed in all evaluable biopsies (baseline sample from patient N11 was not evaluable because of a lack of Sox10/S100 stained cells)." (PMID 36089578, 2022). "The BF multiplex IHC staining was performed using different combinations of six immune-cell markers—CD3, CD4, CD8, CD20, CD68 and CD163—and the melanoma cell marker SOX10." (PMID 35954345, 2022). "In contrast, SOX10+MITF– melanoma cells had acquired expression of several NC lineage genes as compared with differentiated melanocytes." (PMID 36040798, 2022). "Expression of “melanoma cocktail” (SOX10, S100, HMB45, and MelanA) along with ki67 remain vital for diagnosing nevoid melanoma." (PMID 36289768, 2022). "Strikingly, similar to the MITFlo phenotype, reduced expression of SOX10 in melanoma has been shown to confer resistance to MAPK pathway inhibition." (PMID 36040798, 2022). "When analyzed separately, the intensity level of SOX10 was also significantly higher for primary melanomas (n = 10; p = 0.02) and for subcutaneous metastases (n = 5, p = 0.002) when compared with both organ and lymph-node metastases (n = 15)." (PMID 36361209, 2022). "Evidence of intratumoral heterogeneity was supported further at the protein level by IHC analysis of melanomas showing clusters of tumor cells with either low or high expression of SOX10." (PMID 35296667, 2022). "In this study, we determine the functional and transcriptional phenotypes of melanoma cells with retained or loss of MITF and SOX10 expression, respectively." (PMID 36040798, 2022). "We introduced the nuclear marker specific for melanoma cells SOX10 to our optimized double-labeling protocols." (PMID 35954345, 2022). "The re-emergence of an NCP transcriptional program in melanoma is supported by the upregulation of other neural crest-related genes in tumors such as sox10, dlx2a, ednrb, Brn3, and FOXD17,14–17." (PMID 34099848, 2021). "The results of double labeling of Sox10 with CD44 (melanoma stem cell marker) revealed that specific nucleus Sox10 expressed in melanocyte stem cell within the bulge (a1-b4), anagen hair bulb (b5-b7) and epithelial strand in catagen (c1-c4)." (PMID 34522176, 2021). "In our study, we initially found that elevated SOX10 can affect glucose consumption, lactate production and ATP levels and consequently promote melanoma cell proliferation." (PMID 34249897, 2021). "Treatment with either dabrafenib and trametinib or with RGS, increased CD40+SOX10+ melanoma cells in the tumors of melanoma patients and patient-derived xenografts." (PMID 34092233, 2021). "SOX10 was previously shown to be necessary for melanoma formation and maintenance by controlling cell survival and cell cycle." (PMID 34874265, 2021). "In melanoma, core regulators of neural crest lineage, MITF and SOX10, regulate the emergence of distinct cell states associated with drug tolerance establishment after treatment." (PMID 34071428, 2021). "Here we used ATAC-Seq analysis of multiple zebrafish melanoma tumors to identify recurrently open chromatin domains as putative melanoma-specific sox10 enhancers." (PMID 34099848, 2021). "Expression levels of SOX9 were negatively correlated with those of SOX10 levels in the TCGA primary melanoma tissue data set; however, it is lower than the GEO data set." (PMID 34526609, 2021). "This is consistent with prior studies demonstrating SOX10 as a marker and promotor of invasiveness in melanomas." (PMID 33842927, 2021).
melanoma (continued). "For instance, the transcription factors PAX3, FOXD3, and SOX10 are part of a gene regulatory network in early NC development that also supports melanoma cell growth, migration, and resistance to targeted therapy, respectively." (PMID 34417458, 2021). "Ongoing studies continue to decipher the embryonic function of sox10 in zebrafish, but to date, regulation of sox10 expression in melanoma is poorly understood." (PMID 34099848, 2021). "As NGFR was proven to be useful for the diagnosis of desmoplastic melanoma, SOX10 was discovered to be as valuable." (PMID 34449584, 2021). "In this study, we screened individual putative sox10 regulatory elements for activity within NCCs and melanoma in zebrafish." (PMID 34099848, 2021). "In normal skin tissue, SOX10 nuclear staining was found only in the basal epidermal cells, whereas extensive SOX10-positive cells were found in the dermis of lgCMN and melanoma tissues." (PMID 34912899, 2021). "In line with this, it is well-understood that SOX10 expression is required for melanoma formation in NRAS-mutant mouse melanomas." (PMID 34930891, 2021). "It is therefore likely that a negative feedback relationship exists for the regulation of PITX1 and miR-19b via SOX10 expression in melanoma cells." (PMID 34526609, 2021). "A large number of other melanocytic markers have been subsequently investigated including HMB45, Melan A, tyrosinase, MITF, and SOX10, and are increasingly used in the diagnosis of melanoma." (PMID 34449584, 2021). "It has been shown that YTHDF2 targets a plethora of mRNAs for degradation in cancers, such as, TNFR2, c-Myc and CEBPA in leukemia, EGFR, IL11, SERPINE2 and SOCS2 in liver cancer, and PD-1, CXCR4, and SOX10 in melanoma." (PMID 33658012, 2021). "One highly upregulated neural crest gene in melanoma in both zebrafish and humans is sox10, a transcription factor necessary for neural crest development." (PMID 34099848, 2021). "More specific melanoma markers such as Melan-A, HMB-45, SRY-related HMG-box 10 (SOX-10), microphthalmia-associated transcription factor (MiTF) and tyrosinase, should be used together with S100 protein for accurate differential diagnosis." (PMID 34514560, 2021). "Together, developmentally incorrect activation of sox10 enhancers in zebrafish and human melanomas suggests that understanding the activity and contribution of individual enhancers within this locus will illuminate earlier initiating steps of melanoma." (PMID 34099848, 2021). "In various neoplasms, SOX10 expression is found in melanomas, epithelial neoplasms, astrocytomas and oligodendrogliomas." (PMID 33536079, 2021). "Beyond melanoma, SOX10 has been shown to mediate mammary duct cell state interconversion and promote de-differentiation to a more stem/progenitor state characterized by a neural crest-like phenotype in breast tumors." (PMID 34071428, 2021). "Collectively, ATAC-Seq analysis of zebrafish melanoma tumors reliably identifies transcriptional regulatory regions near sox10 that function as enhancers with neural crest cell activity in transgenic reporter studies." (PMID 34099848, 2021). "Nevertheless, a study in melanoma cells reported that, when SOX10 is phosphorylated by ERK1/2, its SUMOylation at K55 is prevented, resulting instead in the inhibition of its transcriptional activity upon multiple target genes, including MITF." (PMID 34356679, 2021). "Intriguingly, another study showed that SOX9 and SOX10 are functionally antagonistic regulators of postnatal melanocyte and melanoma development." (PMID 34526609, 2021). "As expected, we observed CD40+SOX10+ melanoma cells in the TME of all 11 post-treatment samples and in 10 of 11 pretreatment samples." (PMID 34092233, 2021). "(A) Overexpression of SATB2 with TETon (iSATB2) in normal human epidermal melanocytes (HEMA-LP) and in SKMEL2, SKMEL28, and A375 melanoma cells is sufficient to induce transcriptional activation of SOX10, SNAI1/2, PDGFB, and SEMA3F mRNA." (PMID 33527896, 2021).